PPP1R8 (protein phosphatase 1 regulatory subunit 8)
Description:
Inhibitor subunit of the major nuclear protein phosphatase-1 (PP-1). It has RNA-binding activity but does not cleave RNA and may target PP-1 to RNA-associated substrates. May also be involved in pre-mRNA splicing. Binds DNA and might act as a transcriptional repressor. Seems to be required for cell proliferation. Isoform Gamma is a site-specific single-strand endoribonuclease that cleaves single strand RNA 3' to purines and pyrimidines in A+U-rich regions. It generates 5'-phosphate termini at the site of cleavage. This isoform does not inhibit PP-1. May be implicated in mRNA splicing.
Synonyms: NIPP-1; ARD1; NIPP1; ard-1; PRO2047
Tractability: PROTAC: ubiquitination databases record sites on it; its protein half-life has been measured.
Gene: Protein-coding gene on chromosome 1 (27,830,782 to 27,851,676, forward strand). Ensembl gene ENSG00000117751.
Subcellular location: Nucleus; Nucleus speckle; Cytoplasm (Isoform Gamma)
Subcellular location (Human Protein Atlas): Nuclear speckles; Nucleoplasm
Pathways (Reactome):
Metabolism of RNA: mRNA Polyadenylation; mRNA Splicing - Major Pathway
Gene Ontology:
Molecular function: molecular function inhibitor activity; protein binding; mRNA binding; protein serine/threonine phosphatase inhibitor activity; ribonuclease E activity; RNA binding; protein phosphatase regulator activity
Biological process: RNA catabolic process
Cellular component: nuclear speck; nucleoplasm; nucleus; cytoplasm
Genetic constraint (gnomAD): Loss-of-function variants: 4 observed, 27.77 expected, observed/expected ratio (o/e) 0.14, 90% interval 0.07 to 0.33. The upper end of that interval is the gene's LOEUF score, 0.33, which puts it in group 1 of 6, group 1 being the genes least tolerant of losing a copy. Missense variants: 251 observed, 433.02 expected, observed/expected ratio (o/e) 0.58, 90% interval 0.52 to 0.64. Synonymous variants: 166 observed, 170.02 expected, observed/expected ratio (o/e) 0.98, 90% interval 0.86 to 1.11.
Homologues: Orthologues: chimpanzee PPP1R8 (100% identical), dog PPP1R8 (99% identical), mouse Ppp1r8 (98% identical), rat Ppp1r8 (97% identical), guinea pig PPP1R8 (97% identical), macaque STX12 (96% identical), pig PPP1R8 (95% identical), rabbit PPP1R8 (91% identical), tropical clawed frog ppp1r8 (84% identical), zebrafish ppp1r8a (77% identical), zebrafish ppp1r8b (73% identical), Drosophila melanogaster NiPp1 (48% identical), and 1 more. Paralogues in human: SLC4A1AP (29% identical), SNIP1 (12% identical).
Diseases named in the same sentence as PPP1R8 in open-access papers:
PPP1R8 is named in the same sentence as 22 diseases in open-access papers, as found by Europe PMC text mining. Sharing a sentence is not in itself a finding about the gene and the disease. The quoted sentences say what the papers report.
glioma (3 papers, 2021 to 2025). A benign or malignant brain and spinal cord tumor that arises from glial cells (astrocytes, oligodendrocytes, ependymal cells). "Notably, a similar effect has been observed in PPP1R8-deficient low-grade glioma cells, where reduced proliferation was linked to cell cycle arrest." (PMID 40842996, 2025). "While the role of PPP1R8 has been investigated in LGG, where its deficiency has been shown to decrease cell proliferation and the proportion of cells in the G2/M and S phases while increasing the G0/G1 population, its role in GBM, a highly aggressive glioma, remains unexplored." (PMID 40842996, 2025). "Furthermore, we could identify several novel glioma biomarkers likely helpful in both diagnosis and prognosis of the patients, including the genes PPP1R8, GPBP1L1, KIAA1614, C14orf23, CCDC77, BVES, EXD3, CD300A, and HEPN1." (PMID 38812741, 2024). "Taken together, our findings indicate that PPP1R8 plays a crucial role in promoting GBM cell proliferation, highlighting its potential as a therapeutic target in aggressive gliomas." (PMID 40842996, 2025).
hepatocellular carcinoma (2 papers, 2020 to 2025). A malignant tumor that arises from hepatocytes. "Furthermore, hypoxia-induced activation of PPP1R8 has been linked to enhanced metastatic potential and poor prognosis in hepatocellular carcinoma, suggesting a role for PPP1R8 in cancer progression." (PMID 40842996, 2025).
breast carcinoma (1 paper, 2025). "Additionally, PPP1R8 has been implicated in tumorigenesis through its role in cell proliferation and survival in several cancers, such as Kidney Renal Clear Cell Carcinoma and breast cancer." (PMID 40842996, 2025).
glioblastoma (1 paper, 2025). The most malignant astrocytic tumor (WHO grade IV). "Further in-depth in vitro and in vivo studies are warranted to delineate the molecular mechanisms by which PPP1R8 contributes to glioblastoma progression." (PMID 40842996, 2025).
HCMV infection (1 paper, 2024). "Our findings indicate that HCMV infection disrupts PP1 function through the temporal dysregulation of at least nine recognized regulatory subunits, PPP1R10, PPP1R7, YLPM1, PPP1R11, PPP1R9A, PPP1R8 (NIPP1), PPP1R9B, PPP1R12C, and URI1." (PMID 39772267, 2024).
cancer (6 papers, 2012 to 2025). A tumor composed of atypical neoplastic, often pleomorphic cells that invade other tissues. "Emerging evidence suggests that PP1/PPP1R8 functions as a molecular regulator of directed cell migration by upregulating Cdc42 signaling, potentially enhancing the migratory properties of cancer cells." (PMID 40842996, 2025). "In addition to known cachexia genes such as FOXO1, novel genes from muscle, including PPP1R8 and AEN correlated with cancer weight loss." (PMID 33923976, 2021). "To assess PPP1R8 expression, we examined its mRNA levels across the NCI-60 cancer cell line panel, including GBM cell lines." (PMID 40842996, 2025).
PPP1R8 also shares sentences with these, for which no sentence is quoted: infection (10 papers); tumor (6); prostate carcinoma (2); cervical cancer (1); colorectal (1); diabetes (1); Infertility (1); liver disease (1); lung carcinoma (1); male infertility (1); neuroblastoma (1); oligodendroglioma (1); papilloma (1); prostate tumours (1); skin carcinoma (1); xeroderma pigmentosum (1).